BCL2 (BCL2 apoptosis regulator)
Diseases named in the same sentence as BCL2 in open-access papers (continued):
Sharing a sentence is not in itself a finding about the gene and the disease.
B-cell lymphoma (continued). "B cell lymphoma with dual expression of c-MYC and BCL2 (double-expressor lymphoma, DEL) accounts for approximately one-third of DLBCL cases." (PMID 32695674, 2020). "In the revised fourth edition of the World Health Organization (WHO) classification of lymphoid neoplasms published in 201615, DH/triple-hit (TH) DLBCL was reclassified as high-grade B-cell lymphoma, with MYC and BCL2 and/or BCL6 rearrangements." (PMID 33168821, 2020). "The BCL-2 inhibitor venetoclax has been approved for use in B cell lymphoma such as CLL and is now being investigated in an ongoing phase II trial in patients with BCL-2-positive TCL, including AITL and TFH origin PTCL (NCT03552692)." (PMID 32448357, 2020). "In conclusion, we described a rare EBV-negative high-grade B-cell lymphoma with MYC and BCL2 rearrangements of the male breast." (PMID 33339535, 2020). "Aggressive B-cell lymphomas gain MYC and BCL2 alterations through mechanisms other than gene translocations, and 18–44% of DLBCLs have been reported to express MYC and BCL2 concurrently." (PMID 33182440, 2020). "This study aims to elucidate the patterns of BCL6, BCL2 and C-MYC gene aberrations among Malaysian B-cell Non-Hodgkin Lymphoma (NHL) using fluorescence in situ hybridization (FISH)." (PMID 31892985, 2020). "High-grade B-cell lymphoma with rearrangements of MYC and BCL2 and/or BCL6 is an aggressive mature B-cell neoplasm, whereas B-lymphoblastic lymphoma is immature cell proliferation, with a frequent positivity for terminal deoxynucleotidyl transferase." (PMID 32713346, 2020). "Being initially considered as Burkitt lymphoma, we here rendered the diagnosis of a so-called “high-grade B-cell lymphoma with MYC and BCL2 rearrangements” also called “double-hit lymphoma” with Burkitt morphology." (PMID 33339535, 2020). "In support of our study, the mutation signature associated with FL was also the characteristic change in high-grade B-cell lymphoma with MYC and BCL2 translocations, and in the EZB or C3 genetic subgroup, which are enriched by BCL2 translocation." (PMID 31844144, 2020). "An initial diagnosis of an aggressive mature B cell lymphoma should incorporate the assessment of cytological and immunohistochemical features, including the COO, and the percentage of MYC- and BCL2-expressing cells." (PMID 31388760, 2019). "MYC/BCL double-hit lymphomas (DHL) are high-grade B cell lymphomas with MYC and BCL2 or BCL6 translocations." (PMID 31336613, 2019). "HGBL, with MYC and BCL2 and/or BCL6 and HGBL, NOS replaces the 2008 category of B-cell lymphoma, unclassifiable, with features intermediate between DLBCL and Burkitt lymphoma (BCLU)." (PMID 31484540, 2019). "High grade B-cell lymphomas include the entities carrying MYC, BCL2 and/or BCL6 translocations or cases with blastoid morphology without DH translocations." (PMID 31942539, 2019). "A B-cell lymphoma with a combination of C-MYC and BCL-2 or BCL-6 translocations is called a Double-Hit lymphoma (DHL), and the one with three gene translocations is called a Triple-Hit lymphoma (THL)." (PMID 30666200, 2018). "High grade B cell lymphoma with DH/TH (i.e. concurrent translocations of MYC and BCL2, and/or BCL6) has an adverse prognosis (Grade 2B)." (PMID 30190794, 2018). "In parallel with experiments on DH-My6 cells, four B-cell lymphoma cell lines with a GCB type, including two DLBCL cell lines (Su-DHL-5 and HT) and two MYC/BCL2 DHL cell lines (Su-DHL-10 and Nu-DHL-1), were also tested." (PMID 30323893, 2018). "BCL-2 is detectable in approximately 50% of DLBCL and 75% of high-grade B-cell lymphomas, whose effect is to inhibit cell apoptosis and promote cell proliferation, which interacts with the action of C-MYC." (PMID 30666200, 2018). "Considering these cytogenetics findings in the context of the revised 2017 WHO classification system, the DLBCL component should be designated “high-grade B-cell lymphoma with MYC and BCL2 rearrangements”." (PMID 29793519, 2018).
B-cell lymphoma (continued). "In the light of the newly shaped entity of high-grade B-Cell lymphoma with MYC, BCL2 and or BCL6 aberrations, which was excluded from the current study, however, this was to be expected." (PMID 29731969, 2018). "Patients with B cell lymphomas bearing MYC translocation combined with translocation involving other genes, such as BCL2, BCL3, or BCL6, defined as double-hit lymphoma (DHL), have a poor prognosis." (PMID 28595585, 2017). "In aggressive B-cell NHL, the importance of MYC and BCL2 proto-oncogene coexpression (as assessed by immunohistochemistry) and high-grade histologic features are particularly noteworthy." (PMID 28321348, 2017). "DHL typically refers to both DHL and THL, and are currently classified as high-grade B-cell lymphoma, with MYC and BCL2 and/or BCL6 rearrangements in the 2016 revision of the WHO classification of lymphoid neoplasms." (PMID 28379189, 2017). "According to the 2016 WHO classification revision, patients with DH translocations should be excluded from the DLBCL NOS category and placed within the novel category “High-grade B-cell lymphomas, with MYC and BCL2 or BCL6 translocations”." (PMID 29088292, 2017). "Here, both in vitro and in vivo, our study characterized a Bcl-2-dependent inhibition of ABT-199 on tumor angiogenesis, mediated by intrinsic miR21-Treg cell pathway, leading to sensitizing effect of ABT-199 on B-cell lymphoma." (PMID 28637496, 2017). "In another study, Oki et al21 analyzed the outcome of 129 cases of DHL at MD Anderson; DHL was defined as B-cell lymphoma with translocations and/or extra signals involving MYC plus BCL2 and/or BCL6." (PMID 27115017, 2016). "Double hit lymphoma represents up to 14% of the patients with aggressive B-cell lymphoma and MYC/BCL2 DHL is most common, representing approximately 65% of all cases, followed by MYC/BCL2/BCL6 triple hit lymphoma, ~20%, and MYC/BCL6 DHL, ~15%." (PMID 27203548, 2016). "In this retrospective study, we assess 157 patients with MYC/BCL2 DHL including 108 patients with de novo disease and 49 patients with a history of FL or rarely other types of low-grade B-cell lymphoma." (PMID 27203548, 2016). "To address these issues, we systematically studied the clinicopathologic features of 157 patients with MYC/BCL2 DHL including 108 with de novo disease and 49 patients with a history of low-grade B-cell lymphoma, mostly FL." (PMID 27203548, 2016). "Double-hit lymphomas (DHLs) are a heterogeneous group of mature B-cell lymphomas that harbor rearrangements of MYC and BCL2." (PMID 27606052, 2016). "In the same set of large B-cell lymphomas, the ratio of STAT3pSer727 within the total pool of STAT3 also correlated positively (+0.9104) with the ratio of Bcl-2pSer70 in the total pool of Bcl-2." (PMID 26430964, 2015). "The term ‘DH lymphoma’ was initially used to describe mature-B-cell lymphomas with a chromosomal breakpoint affecting the MYC locus in combination with another recurrent breakpoint, such as BCL2, BCL6, BCL3 or CCND1." (PMID 26517511, 2015). "Heightened expression of both Myc and Bcl-2 is a highly potent combination (highest in MZCD9+) promoting survival during Myc-driven proliferation and frequently occurs in various B-cell lymphomas." (PMID 25717326, 2015). "Biopsy was performed from skin lesion which was reported as CD20+, BCL2+, MUM1+, BCL6+ high grade B cell lymphoma infiltration." (PMID 26457084, 2015). "We thus tested the activity of ABT-263, a dual Bcl-2/Bcl-X inhibitor, to restore I-BET762-mediated apoptosis in all resistant B-cell lymphoma cell lines." (PMID 26658189, 2015). "We analyzed 46 B-cell lymphoma (B-NHL) specimens with known karyotypes for translocations of IGH-, BCL2-, BCL6- and MYC-genes." (PMID 24733537, 2014). "The translocation identified in B-cell lymphoma positions BCL-2 under the control of the immunoglobulin heavy-chain promoter, leading to massive BCL-2 over-expression and subsequent resistance to cell death." (PMID 25621172, 2014).
B-cell lymphoma (continued). "Nevertheless, there is evidence that suggests that rituximab would increase cytotoxic effects of alkylating agents by inhibiting interleukin-10 that results in downregulation of Bcl-2 and sensitization of CD20+ B cells lymphoma to apoptosis." (PMID 23029628, 2012). "However, MYC-driven B cell lymphomas, particularly HGBCL with MYC and BCL2 rearrangements, frequently silence surface BCR/CD79B expression, limiting the therapeutic reach of CD79B-directed ADCs and underscoring the need for complementary treatment strategies." (PMID 41668618, 2026). "The immunophenotypic profile-predominance of CD20+ and PAX 5+ B cells with BCL6 expression and BCL2 negativity is characteristic of reactive nodal or cutaneous lymphoid hyperplasia, as opposed to most B-cell lymphomas." (PMID 40559769, 2025). "Subclassification into these entities is important to evaluate prognosis and treatment options, as some subtypes, such as diffuse large B-cell lymphoma/high-grade B-cell lymphoma with MYC and BCL2 rearrangements (DLBCL/HGBL-MYC/BCL2), have worse prognosis and require alternative treatment regimens." (PMID 39790106, 2025). "Notably, the classification of high-grade B-cell lymphoma characterised by dual rearrangements involving MYC and either BCL2 or BCL6 has been redefined as DLBCL with high-grade B-cell lymphoma with MYC/BCL2 (DLBCL/HGBL-MYC/BCL2)." (PMID 40572636, 2025). "However, the relationship between BCL2 and SOX9 in haematological malignancies, especially B‐cell lymphoma, is poorly understood." (PMID 40356256, 2025). "This had been used to argue for the classification of rare cases of TdT‐positive blastoid B‐cell lymphoma with both MYC and BCL2 translocations as B‐LBL in the revised fourth edition of the World Health Organization classification of haematolymphoid tumours (WHO‐HAEM4R)." (PMID 41047873, 2025). "This rearrangement should be investigated in FL cases lacking BCL2 expression on IHC to distinguish FL from other low-grade B-cell lymphomas, such as marginal zone lymphoma." (PMID 40881873, 2025). "Histopathologic analysis revealed a malignant B-cell lymphoma with a MYC gene rearrangement in the absence of BCL2 or BCL6 rearrangements, consistent with a high-grade lymphoma." (PMID 41362384, 2025). "In our case, image-guided core biopsy demonstrated a CD20-positive, MYC-rearranged B-cell lymphoma with a nearly 100% Ki-67 proliferation index and no BCL2 or BCL6 rearrangements." (PMID 41362384, 2025). "Furthermore, cytogenetic profiling is crucial in identifying MYC, BCL2, and BCL6 rearrangements in high-grade B-cell lymphomas (HGBL-MYC/BCL2/BCL6), which define cases with aggressive clinical behavior and poor prognosis." (PMID 40150070, 2025). "As many as 19% of patients had high-grade B-cell lymphoma with MYC and BCL2 or BCL6-Rearrangement." (PMID 38893108, 2024). "Large B-cell lymphomas with a MYC rearrangement, along with B-cell lymphoma 2 (BCL2) and/or B-cell lymphoma 6 (BCL6) rearrangements, are being classified as high-grade B-cell lymphomas (HGBLs) and are frequently referred to as double-hit (DHL) and triple-hit lymphomas (THL), respectively." (PMID 38397877, 2024). "The FISH analysis showed the C-MYC and BCL-2 gene rearrangement, indicating a definitive diagnosis of a “double-hit” high-grade B cell lymphoma (centroblast, non-GCB type)." (PMID 40078480, 2024). "High-grade B-cell lymphoma with MYC and BCL2 rearrangements was detected in 9% of all large B-cell lymphoma specimens, including one case with rearrangements at all three loci MYC, BCL2, and BCL6; MYC and BCL6 rearrangements were found in 1.6% of specimens." (PMID 38903717, 2024). "FNAB with cell block is an equally effective alternative to core biopsy and excisional biopsy for assessment of MYC, BCL2, and BCL6 FISH, which is required for identification of the clinically aggressive subset of large B-cell lymphomas that carry both MYC and BCL2 rearrangements." (PMID 38903717, 2024).
B-cell lymphoma (continued). "In addition, important adaptations have also been made in the previous category of high-grade B-cell lymphomas with dual rearrangements of MYC and BCL2 and/or BCL6 of the WHO-HAEM4R." (PMID 38835969, 2024). "B-cell lymphomas with MYC, BCL2, BCL6, and CCND1 rearrangements are rare entities." (PMID 38914869, 2024). "The term high-grade B-cell lymphoma with dual rearrangements of MYC and BCL2 and/or BCL6 from the previous edition of WHO has been conceptually reframed and reassigned to diffuse large B-cell lymphoma/high-grade B-cell lymphoma with MYC and BCL2 rearrangements (DLBCL/HGBL-MYC/BCL2)." (PMID 39038016, 2024). "Importantly, 5%-15% of large B-cell lymphomas bear a translocation in MYC and BCL2 or BCL6, and 20%-30% of the cases are double expressors." (PMID 37457123, 2023). "This entity does not include aggressive B-cell lymphomas with IRF4 rearrangements that also harbor BCL2 and/or MYC rearrangements." (PMID 36460764, 2023). "This case carried a BCL2 rearrangement which is only rarely found in indolent B-cell lymphoma outside the context of follicular lymphoma and had not previously been reported in SDRPL." (PMID 37656249, 2023). "However, Bcl-2 is only expressed on the cell surface of B-cell lymphomas, and the pathological types of PCNSL include peripheral T-cell lymphomas in addition to B-cell lymphomas." (PMID 37056341, 2023). "Only 12 cases (2.8%) were true new entities, including seven cases of high-grade B-cell lymphoma NOS, three of anaplastic large B-cell lymphoma, ALK-negative, 1 case of HHV8+ DLBCL NOS, and 1 of high-grade B-cell lymphoma with C-MYC and BCL2/BCL6 rearrangement." (PMID 35932211, 2022). "Especially when combined with a BCL2 and/or BCL6 rearrangement (high-grade B-cell lymphoma with MYC and BCL2 and/or BCL6 rearrangement), these DLBCL have a poor outcome when treated with standard R-CHOP chemotherapy, and may require a different treatment." (PMID 32979109, 2021). "Here we report the clinical, histological and immunohistochemical characterization of a canine subset of MYC and BCL2-negative, high-grade B-cell lymphomas sharing similarities with B-LL." (PMID 33816589, 2021). "Given the importance of balanced BCL2 and BIM protein levels for controlling normal B cell survival and suppressing B cell lymphoma, it would not be surprising that BCL2 protein turnover be governed by multiple, redundant ubiquitin ligases." (PMID 33914737, 2021). "Our cohort included samples from chronic lymphocytic leukemia (CLL), follicular lymphoma (FL), diffuse large B-cell lymphoma (DLBCL), high-grade B cell lymphoma with translocations in MYC and BCL2 (HGBL-DH), mantle cell lymphoma (MCL) and marginal zone lymphoma (MZL)." (PMID 33670870, 2021). "Between five and ten percent of DLBCL have concurrent rearrangements of MYC, BCL2, and/or BCL6 and are now recognized as a distinct entity in the 2016 WHO classification of lymphoid neoplasms as ‘high-grade B-cell lymphoma with MYC, BCL2, and/or BCL6 rearrangements (DHL/THL)’." (PMID 34830747, 2021). "The 2016 revised World Health Organization guidelines of lymphoid neoplasms classified large B-cell lymphoma with rearrangements of MYC and BCL2 or/and BCL6 in a distinct category to be designated high-grade B-cell lymphoma, also called double-hit lymphoma (DHL) or THL." (PMID 34113336, 2021). "Therefore, our data suggested that AID is a poor prognostic marker of High-grade B-cell lymphoma with MYC and BCL2 and/or BCL6 rearrangements, as it has a different pathological background." (PMID 34945004, 2021). "In addition, in a subset of so called double- or triple-hit B-cell lymphomas concurrent translocations involving MYC and BCL2 and/or BCL6 occur." (PMID 34210001, 2021). "High grade B-cell lymphoma with MYC and BCL2 rearrangements (HGBL-DHL), formerly termed double-hit lymphoma (DHL) which constitutes 5–10% of histologically diagnosed diffuse large B-cell lymphoma (DLBCL), is currently classified as a unique and separate entity." (PMID 33777762, 2021).
B-cell lymphoma (continued). "The prognostic implications of DHL and THL underlie the 2017 World Health Organization (WHO) update, which includes the cytogenetically defined category of “High grade B cell lymphoma with MYC and BCL2 and/or BCL6 rearrangements” (DHL/THL) as its own distinct entity." (PMID 31932576, 2020). "The debate about research into aggressive mature B-cell lymphomas with MYC, BCL2 and/or BLC6 aberrations, defined as high-grade B-cell lymphoma with double or triple hit (HGBL-DH/TH), deserves a special section as their detection constitutes a principal goal according to the last WHO classification." (PMID 31940809, 2020). "C-MYC, BCL2 and BCL6 genes are the most commonly oncogenes involved in B-Cell lymphomas." (PMID 31892985, 2020). "Of note, with these studies, it became clear that CD79 and MYD88 mutations were mutually exclusive with other known recurrent alterations occurring in DLBCLs, such as translocations of MYC and BCL2 and/or BCL6, as observed in the new WHO category of high-grade B-cell lymphomas." (PMID 33050534, 2020). "High-grade B cell lymphomas with rearrangements on C-MYC and BCL2 and/or BCL6 (HGBL with MYC and BCL2 and/or Bcl6 rearrangement) are associated with worse clinical outcomes and thus were introduced as a separate new category in the recently updated WHO classification." (PMID 32613279, 2020). "Therefore, diagnosis of a high-grade B-cell lymphoma with MYC and BCL2 rearrangements that transformed from a low-grade follicular lymphoma was rendered." (PMID 32183313, 2020). "Hence, the study aims to characterize the patterns of BCL6, BCL2 and C-MYC gene aberrations in Malaysian B-cell NHL using interphase FISH." (PMID 31892985, 2020). "The poor outcome of high-grade B-cell lymphoma, with rearrangements of MYC, BCL2 and/or BCL6, also known as double-hit lymphoma or triple-hit lymphoma (DHL or THL), has been well documented, while the clinical significance of extra copies of MYC, BCL2 or BCL6 are still less well known." (PMID 31315646, 2019). "Rearrangements of MYC, BCL2, and/or BCL6 can be demonstrated using conventional cytogenetic techniques (karyotype) and/or FISH; this is a requirement for the diagnosis of cases of high-grade B cell lymphoma with DH/TH (Grade 2A)." (PMID 30190794, 2018). "In recognition of its unique biology and clinical behavior, DHL has been included in the 2016 revision of the World Health Organization (WHO) classification of lymphoid neoplasms as a new category of “high-grade B-cell lymphoma (HGBL) with MYC and BCL2 or BCL6 rearrangements”." (PMID 30323893, 2018). "Indeed, some studies have shown that B-cell lymphomas with concurrent MYC and BCL2 abnormalities, other than translocations, appear to behave similarly to MYC/BCL2 double-hit lymphomas." (PMID 28212447, 2017). "They studied 33 low-grade B cell lymphomas without a BCL2 break and compared the results with cases that had a BCL2 break." (PMID 27398102, 2016). "Thirty-three low-grade B cell lymphomas without a BCL2 rearrangement were studied for recurrent morphological features." (PMID 26949422, 2016). "MYC/BCL2 DHL has been well studied in the literature and yet no studies have systemically compared the clinicopathologic features of patients who present with de novo disease versus patients with a history of low-grade B-cell lymphoma, mostly FL, and then develop MYC/BCL2 DHL." (PMID 27203548, 2016). "However, most of what we know about double-hit B-cell lymphoma is derived from studies of the most common form, MYC/BCL2 DHL." (PMID 26573234, 2016). "CD20+, BCL2+, MUM1+, BCL6+ high grade B cell lymphoma infiltration was detected with skin biopsy." (PMID 26457084, 2015). "In addition, EZH2 cooperates with BCL2 and BCL6 to create the GCB phenotype and induce B-cell lymphomas through formation and repression of bivalent chromatin domains." (PMID 26654227, 2015).